CCR10 (C-C motif chemokine receptor 10)
Diseases named in the same sentence as CCR10 in open-access papers (continued):
Sharing a sentence is not in itself a finding about the gene and the disease.
glioma (8 papers, 2014 to 2024). A benign or malignant brain and spinal cord tumor that arises from glial cells (astrocytes, oligodendrocytes, ependymal cells). "Overall, it is only known that the CCL27/CCR10 axis can mediate glioma cell proliferation and invasion and is involved in T-cell-mediated skin inflammation." (PMID 38612597, 2024). "An immunohistochemical retrospective study of 60 gliomas showed that high CCR10 expression, which was observed in about half the tumors, correlated with poor survival." (PMID 35740564, 2022). "After mechanism validation both in vitro and in vivo, we demonstrated that p-Akt was key downstream signal involved in CCL27/CCR10 mediated proliferation and invasion of glioma." (PMID 25149529, 2014). "Together, these data demonstrates that CCR10 activation impacts proliferation and invasion of glioma in vitro." (PMID 25149529, 2014). "In summary, these data indicate that CCR10 regulation of p-Akt expression has significantly clinical impact on glioma." (PMID 25149529, 2014). "Consistent with the TCGA data, Rembrandt data and qRT-PCR assay confirmed the robust expression of CCR10 in glioma tissue and cell lines." (PMID 25149529, 2014). "Consistent with the expression data, we found robust expression of CCR10 in 6 glioma cells, neurosphere and xenograft models at levels 5.81–19.13 folds higher than the levels observed in a control brain tissue." (PMID 25149529, 2014). "Kaplan-Meier survival analysis demonstrated that CCR10 shRNA significantly prolonged survival of glioma in NOD/SCID mice." (PMID 25149529, 2014). "We propose the linkage between CCR10 and p-Akt, both of which play critical roles in carcinogenesis, has advanced our knowledge of how CCR10-overexpressing cancer cells mediated the glioma malignant." (PMID 25149529, 2014). "In summary, we show here that CCR10 is expressed in glioma and found that CCR10 expression correlates with poor survival of GBM patients." (PMID 25149529, 2014). "Moreover, CCR10 is highly expressed in human glioblastoma brain tissue; therefore, this receptor seems to be essential for glioma proliferation and invasion." (PMID 38612597, 2024). "Taken together, CCR10 may also play an important functional role in increasing the ability of neoplastic cells to grow and invade tissue in glioma." (PMID 25149529, 2014). "In vivo, down-regulation of CCR10 significantly impairs growth of glioma." (PMID 25149529, 2014). "Therefore, p-Akt was involved in CCL27/CCR10 mediated proliferation and invasion of glioma in vitro." (PMID 25149529, 2014). "Furthermore, IHC assay demonstrated CCR10 expression was significantly higher in the glioma samples than in the control brain tissues." (PMID 25149529, 2014). "Treatment of CCR10 siRNA also suppressed the proliferation of glioma in the presence of CCL27." (PMID 25149529, 2014). "Because SRC and PDGF are key upstream mediators of PI3K/Akt signaling pathway, and has been shown to have important roles in cell proliferation, migration and survival, we hypothesized that Akt activation might contribute to CCR10 mediated proliferation and invasion in glioma." (PMID 25149529, 2014). "These immune cells had the highest density in gliomas and possessed immunosuppressive cytokines and chemokines, including CXCL12, CXCL10, CCR5, CCR10, CCL5, and CCR2, to exert their immunosuppressive effects." (PMID 37515314, 2023).
rheumatoid arthritis (7 papers, 2022 to 2025). A chronic, systemic autoimmune disorder characterized by inflammation in the synovial membranes and articular surfaces. "CCR10 has also been implicated in rheumatoid arthritis although the efficacy of inhibiting the receptor on disease pathogenesis remains to be determined." (PMID 40975172, 2025). "Similar to these findings, we previously reported that overexpression of CCL28/CCR10 in synovial tissue was associated with upregulation of angiogenesis in patients with rheumatoid arthritis." (PMID 36713846, 2023). "CCL28 has been linked to the recruitment of Treg cells, however CCL28 and its receptor CCR10 were also proposed to be pathogenic in rheumatoid arthritis." (PMID 35967338, 2022). "Likewise, for TH22/TH17 autoimmune ailments such as rheumatoid arthritis, the application of CCR10 or CCR6 antagonists offers promise in disease management." (PMID 37760825, 2023). "Notably, among those chemokine receptor‐related genes, CCR10, a classical chemokine receptor that facilitates inflammation in the skin and rheumatoid arthritis pathogenesis, was the most significantly upregulated in GCA+ immune cells versus GCA− immune cells." (PMID 37949676, 2023). "CCR10 plays a critical role in the recruitment and function of Th22 cells in diverse inflammatory and pathological contexts, including rheumatoid arthritis (RA), IgA nephropathy (IgAN), and malignant ascites." (PMID 41050670, 2025). "Since rheumatoid arthritis is considered a TH17/TH22-related autoimmune disorder, this report suggests that CCR6 or CCR10 should be considered as potential drug targets." (PMID 37760825, 2023). "We previously observed protein expression of CCL28 and CCR10 to be upregulated by LPS and pro-inflammatory cytokines such as TNF-α and IL-6 in monocytes and macrophages isolated from patients with rheumatoid arthritis (RA)." (PMID 36713846, 2023).
myeloma (6 papers, 2016 to 2025). "Multiple myeloma plasma cell expresses high CCR10 and CCL27 levels in bone marrow, associated with poor prognosis and drug resistance." (PMID 41050670, 2025). "Finally, we found that high tumor CCR10 expression is predictive of worse overall survival in myeloma patients and CCR10 expression is increased in relapsed myeloma tumors relative to newly diagnosed, as well as high-risk genotypes." (PMID 35840578, 2022). "On the cellular therapy frontier, structure-guided CCL27-based CAR T cells targeting CCR10-expressing tumor cells, such as in multiple myeloma, have been described as promising candidates in early proof-of-concept." (PMID 41050670, 2025). "Here, the authors profile the myeloma surfaceome at baseline and in drug resistance, finding the potential target CCR10, and include a streamlined approach to primary sample analysis." (PMID 35840578, 2022). "We verified markedly increased CCR10 expression on myeloma cell lines compared to B-cell malignancy lines, and, importantly, we confirmed expression of CCR10 on CD138+ plasma cells from all ten patient bone marrow aspirates profiled." (PMID 35840578, 2022). "For example, TXNDC11 and CCR10 protein levels appear stable across drug treatments in comparison to canonical myeloma markers BCMA and CD138/SDC1." (PMID 35840578, 2022). "In summary, we found that CCL27, a novel chemokine in the context of the bone marrow microenvironment, confers myeloma drug resistance to proteasome inhibitors by binding to stromal CCR10 and inducing IL-10, a myeloma survival factor." (PMID 27732933, 2016). "We confirmed previously reported CCR10 expression on myeloma cell lines and primary plasma cells in our samples and we found substantial CCR10 expression on stroma cell line HS-5 and primary fibroblasts, which we routinely use as coculture systems." (PMID 27732933, 2016). "CAR-T cells targeting CCR10 in a CCL27-dependent manner eliminate myeloma cells in vitro." (PMID 41050670, 2025). "However, we note that CCR10’s off-tumor expression profile is comparable to other clinically-investigated myeloma CAR-T targets SLAMF7 and CD138, and therefore is not anticipated to be particularly unfavorable." (PMID 35840578, 2022). "Together, these findings suggest CCR10 as a promising immunotherapy target in myeloma." (PMID 35840578, 2022). "Notably, we identified peptides from LILRB4, GGT1, and CCR10, further validating expression of surface markers on primary myeloma cells that we initially highlighted from cell line analysis." (PMID 35840578, 2022). "In summary, we suggest that targeting the CCR10/CCL27 crosstalk in the myeloma microenvironment could contribute to the development of tailored therapeutic interventions bringing multiple myeloma to a chronic, manageable disease or even to cure." (PMID 27732933, 2016). "From our data we suggest that blocking the CCR10/CCL27/IL-10 myeloma-stroma crosstalk is a novel therapeutic target that could be especially relevant in early refractory myeloma patients." (PMID 27732933, 2016). "Knock-down of CCR10 on HS-5 cells by siRNA resensitized cocultured myeloma cells to bortezomib." (PMID 27732933, 2016). "In addition, screening of multiple myeloma surface antigens has identified other promising targets, including CD28 (Tp44), CD48 (BLAST), CD74 (CLIP), CD138 (SDC1), CD229 (SLAMF3), CD319 (SLAMF7), CCR10 (GPR2), TAC1 (NPK), TXNDC11, SLC1A5 (AAAT)." (PMID 41369346, 2025). "First data on the CCR10 antagonist POL7085, a protein epitope mimetic, which was recently successfully used in a model of allergic eosinophilic airway inflammation might pave the way for an application in multiple myeloma." (PMID 27732933, 2016).
asthma (5 papers, 2015 to 2024). "The involvement of CCL28 and its receptors CCR3 and CCR10 has been implicated in inflammatory lung diseases including asthma." (PMID 26112287, 2015). "Further following this hypothetical idea, CCR10+ ILC2s can be considered as interesting candidates for cellular therapy of patients suffering from severe asthma." (PMID 34177944, 2021). "Combined with previous findings, our data further implicate CCR10 in airway inflammatory diseases such as asthma." (PMID 26112287, 2015). "Additional in vitro experiments on airway epithelia cultured under air-liquid interface conditions would be required to further strengthen the dissociation between the inhibitory pathways induced by glucocorticoids and CCR10 antagonists in this asthma model." (PMID 26112287, 2015). "Provided that it will be feasible to ex vivo expand CCR10+ ILC2s under the stable maintenance of their functional properties, it can thus be assumed that asthma patients might benefit from the adoptive transfer and the subsequent intended pulmonary enrichment of these suppressive ILC2s." (PMID 34177944, 2021). "High CCL28 levels are present in airway biopsies from asthma patients, and CCR3+ and CCR10+ cells are recruited to the airways in a CCL28-dependent fashion in murine asthma models." (PMID 39193987, 2024). "Therefore, a CCR10 antagonist may serve as a novel therapeutic in the treatment of asthma." (PMID 28474501, 2017). "Taken together, this evidence suggests relevance for the CCR10/CCL28 axis in respiratory diseases and, in particular asthma." (PMID 26112287, 2015).
glioblastoma (5 papers, 2014 to 2024). The most malignant astrocytic tumor (WHO grade IV). "Furthermore, an enhanced level of CCR10 has recently been associated with poor survival in glioblastoma patients." (PMID 38612597, 2024). "In this study, we report that CCR10 is highly expressed in human glioblastoma and correlated with shorter overall survival and progression-free survival." (PMID 25149529, 2014). "Here we report that the chemokine receptor CCR10 is highly expressed in human glioblastoma compared with control brain tissue." (PMID 25149529, 2014).
autoimmune disease (4 papers, 2020 to 2025). A disorder resulting from loss of function or tissue destruction of an organ or multiple organs, arising from humoral or cellular immune responses of the individual to their own tissue constituents. "However, CCR10 has also been implicated in inflammatory disorders, autoimmune diseases, and cancer progression, where it may facilitate immune evasion and metastasis." (PMID 41050670, 2025). "While CCL28 is responsible for the recruitment of various immune cells (which express CCR10 and CCR3) for mucosal tissue and inflammatory sites, some data indicate that it is responsible for recruiting Treg, maintaining tolerance of self antigens and preventing autoimmune diseases." (PMID 33139632, 2020).
lung fibrosis (4 papers, 2021 to 2025). "Ifabotuzumab-targeted killing of EphA3+ cells significantly reduced the numbers of CCR10+ cells and ameliorated pulmonary fibrosis in humanized NSG mice." (PMID 33945505, 2021). "Thus, human CCR10+ cells promote pulmonary fibrosis, and eliminating these cells inhibits lung fibrosis." (PMID 39768150, 2024). "Targeting CCR10+EphA3+ cells ameliorated lung fibrosis in humanized NSG mice." (PMID 33945505, 2021). "Thus, human CCR10+ cells promote pulmonary fibrosis, and EphA3 mAb–directed elimination of these cells inhibits lung fibrosis." (PMID 33945505, 2021). "Moreover, we have explored a potentially novel targeting approach of CCR10+ cells as a means of preventing and/or ameliorating lung fibrosis." (PMID 33945505, 2021). "The potential of CCR10 as a therapeutic target is suggested by its role in T cell–mediated skin inflammation such as psoriasis and atopic or allergic-contact dermatitis, in addition to its expression on lung epithelial cells in humanized mouse models of idiopathic pulmonary fibrosis." (PMID 40975172, 2025). "Thus, blocking CCR10 may be a useful approach for skin inflammatory diseases, idiopathic pulmonary fibrosis, and enhancing the efficacy of cancer therapies." (PMID 40975172, 2025). "Thus, in the present study, we have investigated the role of CCR10 pathway in fibroblasts and other cell types that may directly contribute to pulmonary fibrosis." (PMID 33945505, 2021). "Together, these findings demonstrate that CCR10+ IPF cells engraft in NSG and NSG-GFP mice, and the presence of these cells positively correlated with lung fibrosis in these mice." (PMID 33945505, 2021). "The introduction of CCR10+ IPF cells into NSG mice initiated and maintained pulmonary fibrosis in this humanized mouse model of IPF." (PMID 33945505, 2021). "Taken together, these findings highlight a role for the signaling pair CCL28/CCR10 in promoting pulmonary fibrosis and enables us to hypothesize that the CCL28/CCR10 axis could also drive fibrosis in SSc." (PMID 38139427, 2023). "Conversely, the therapeutic treatment with KB004 from days 35 to 63 failed to reduce the numbers of Lin–CCR10+ cells and pulmonary fibrosis in humanized NSG mice." (PMID 33945505, 2021).
Allergy (3 papers, 2021 to 2023). An allergy is an immune response or reaction to substances that are usually not harmful. "Finally, several chemokines and chemokine receptors were part of the profile, all with higher value in children who had higher risk for allergy development, with the strongest association found for chemokine receptor-10 (CCR10)." (PMID 33722194, 2021). "Downregulation of CCR10 in allergic horses during clinical allergy suggests an impaired ability of IgE-binding monocytes to home to the skin and maintain skin homeostasis." (PMID 37193769, 2023). "Finally, several chemokines and chemokine receptors, most prominently CCR10, were upregulated in children who later developed allergy." (PMID 33722194, 2021). "Together we report both the coagulation cascade, specifically the genes F13A1, SERPINE1 and C1R, and the CCR10/CCL27 axis, as candidate pathways used by IgE-binding monocytes in the mechanism of allergy." (PMID 37193769, 2023). "TH2 cells (CCR4+ CCR6− CCR10− CXCR3−) orchestrate defense against large extracellular pathogens and helminths by secretion of IL‐4, but are also involved in inflammatory disorders, such as asthma and allergies." (PMID 36740883, 2023). "IL‐9 producing TH9 cells (CCR4− CCR6+ CCR10− CXCR3+) can be induced by the growth factor TGF‐β and IL‐4 from TH2 cells and are similarly involved in immunity against intestinal helminths and onset of allergies." (PMID 36740883, 2023).
atopic dermatitis (3 papers, 2021 to 2025). "Conversely, CCL27/CCR10 are reduced in psoriatic lesions, alopecia areata and hidradenitis suppurativa, while a 2022 meta-analysis links higher to atopic dermatitis (AD) severity, point to disease specific regulation." (PMID 41050670, 2025). "The CCR10/CCL27 axis is important for the skin during homeostatic conditions, and circulating CCL27 is increased in children with atopic dermatitis." (PMID 33722194, 2021).
colorectal cancer (3 papers, 2016 to 2022). A primary or metastatic malignant neoplasm that affects the colon or rectum. "Depletion of CCR10+Treg cells from tumor microenvironment (TME) could be used as an effective treatment strategy for colorectal cancer patients." (PMID 33868236, 2021).
COVID-19 (3 papers, 2021 to 2023). A disease caused by infection with severe acute respiratory syndrome coronavirus 2. "We also found differences in the expression of homing markers on PBs from COVID-19 patients compared to that in healthy controls, with integrin β1 and CCR10 but not CCR9 being expressed on the cells." (PMID 37071584, 2023).
hepatocellular carcinoma (3 papers, 2022 to 2025). A malignant tumor that arises from hepatocytes. "In malignant ascites, elevated CCL27 and infiltration of CCR10-Th22 cells observed in hepatocellular carcinoma, suggest a role for CCR10 in promoting Th22-driven pathology, although its precise function remains to be clarified." (PMID 41050670, 2025). "For instance, Tregs, which abundantly express CCR4, CCR8 and CCR10, were directed to hepatocellular carcinoma (HCC) sites, where their corresponding ligands, CCL22 and CCL28, were present, affecting the treatment outcome by evading the immune system." (PMID 40852716, 2025). "It has been demonstrated that IIN concerning IgA production is involved in some types of cancer, such as hepatocellular carcinoma, which can be activated by CCR9, CCR10, and CXCR4 to promote tumor growth and metastases." (PMID 35883015, 2022).
lymph node metastasis (3 papers, 2005 to 2025). "T lymphocyte density is inversely correlated with CCR10 expression and lymph node metastasis are shown to have a higher expression of CCR10." (PMID 39982274, 2025). "Moreover, the expression of several chemokine receptors has been associated with a greater risk of developing regional and distant metastases as lymph node metastasis (CCR7; CCR10,; CXCR3 and CXCR4;), pulmonary metastasis (CXCR4) or skin metastasis (CCR10;)." (PMID 24559071, 2014). "In particular, they advocated a role for chemokine receptor 7 (CCR7) in lymph node metastasis, CXCR4 in pulmonary metastasis, and CCR10 in skin metastasis." (PMID 15978137, 2005).
ovarian carcinoma (3 papers, 2012 to 2024). A malignant neoplasm originating from the surface ovarian epithelium. "CCR10 is vital for recruiting Treg cells to the TME in ovarian cancer." (PMID 39000453, 2024). "The presence of hypoxia in ovarian cancer triggers the overexpression of CCL28, a ligand specific to CCR10, by tumor cells." (PMID 39000453, 2024). "Frequencies of CCR10-expressing CD39+ Treg were however dramatically lower in the tumor compared to peripheral blood, even though recent findings in human ovarian cancer cell lines show that hypoxia induces CC-chemokine ligand 28 (CCL28) which in turn recruits CCR10-expressing Treg." (PMID 30651930, 2018). "Because CCR1, CCR10 and CXCR4 are not specific receptors for the proinflammatory chemokines released by ovarian cancer cells, these receptors are likely to interact with chemokines released by other cell types such as immune cells and endothelial cells to the microenvironment." (PMID 23300534, 2012).
allergic asthma (2 papers, 2014 to 2015). A asthma with a basis in a pathological type I hypersensitivity reaction. "We therefore explored the pathophysiological role of CCR10 in a murine model of allergic asthma by use of a novel CCR10 antagonist developed from Protein Epitope Mimetic (PEM) technology." (PMID 26112287, 2015). "Potential involvement of the CCR10/CCL28 axis was recently reported in murine models of allergic asthma." (PMID 26112287, 2015). "Moreover, a recent single study has shown that circulating pDCs express increased levels of CCR4 and CCR10 in patients with allergic asthma." (PMID 24877070, 2014).